TGFB1 (transforming growth factor beta 1)
Diseases named in the same sentence as TGFB1 in open-access papers (continued):
Sharing a sentence is not in itself a finding about the gene and the disease.
liver fibrosis (continued). "Additionally, expression of pro-fibrotic genes, including Acta2, Col1a1, and Tgfb1 was significantly higher the CDAA and CDAA + fructose groups in parallel with the differences in liver fibrosis and numbers of activated HSCs." (PMID 29983886, 2018). "If so, FAK signaling not only contribute to the TGFβ1 induced HSC activation, migration, and survival, but also contribute to the TGFβ1 activation through integrins in a feed forward manner to promote HSC activation and liver fibrosis." (PMID 28642549, 2017). "Therefore, TM4SF5 is an important player during TGFβ1 and soluble factor-mediated activation of liver cells, because it regulates ECM production and contributes to the development of liver fibrosis." (PMID 28458469, 2017). "In the context of our in vivo and in vitro observations, the reduction of TGFβ1 and MMP-9 in serum and in stimulated monocytes could be related with reduced monocyte liver infiltration and development of liver fibrosis as previously stated." (PMID 25502575, 2014). "As a critical step of the development of NAFLD, hepatic fibrosis was induced in the mice fed with HFD, shown by upregulating the expression of connective tissue growth factor and transforming growth factor beta 1, which were significantly attenuated by BL153 in a dose-dependent manner." (PMID 24803983, 2014). "While TGFβ1 is increased in serum of patients with NASH and contributes to liver fibrosis secondary to NASH, the role of MMP-9 could apparently have a contradictory role." (PMID 25502575, 2014). "In combination with pro-inflammatory factors, the transforming growth factor beta 1 (TGFβ1) canonical signaling pathway activates hepatic stellate cells (HSCs), leading to collagen deposition in the extracellular matrix (ECM) and the development of liver fibrosis." (PMID 40564168, 2025). "Classical fibrotic mediators and markers (including Tgfb1, Timp1, and Vcam1), collagen of the ECM (including Col4a1, Col4a2, Col16A1, and Col18a1) and cell surface adhesion and signaling integrin (Itga2, Itga5) were found to be differentially expressed in the enriched hepatic fibrosis pathways." (PMID 39747668, 2025). "Puerarin can not only regulate serum enzymes, reduce TGF-β1 production, and inhibit excessive collagen deposition by inhibiting TNF-α/NF-κB, PI3K/Akt, and TGFβ1/Smad signaling pathways, but can also reduce liver fibrosis by inhibiting excessive collagen deposition." (PMID 36358493, 2022). "Moreover, atorvastatin did not mitigate liver fibrosis as evaluated by Sirius red liver staining and by the mRNA expression of fibrotic markers such as αSMA, Col1a1, and Tgfβ1." (PMID 34208774, 2021). "Myricetin also effectively inhibited the expression of TGFβ1, Smad2, phospho-Smad2, Smad3, phospho-Smad3, ERK, phospho-ERK, Akt, and phospho-Akt in the liver of infected mice, suggesting that myricetin attenuated liver fibrosis in mice via modulating TGFβ1 and Akt signaling." (PMID 32373112, 2020). "Upregulation of TGFB1, TGFB2, COL1A1, and COL3A1 were found at W14 post-infection but in both infected and uninfected groups, suggesting that there may be alternative mechanisms for hepatic fibrosis in liver fluke-infected cattle." (PMID 31555289, 2019). "Our finding that hepcidin inhibits transforming growth factor β1 (TGFβ1)-mediated Smad3 phosphorylation by degrading FPN that is upregulated and responsible for the suppression of Akt signalling in activated HSCs, offers the novel therapeutic approaches to overcome liver fibrosis." (PMID 28004654, 2016). "Furthermore, a recent study indicates that hepatitis C virus infection induces TGFβ1 expression through the UPR pathway and this may play a role in liver fibrosis." (PMID 27441395, 2016). "Indeed, nizatidine significantly reduced liver fibrosis measured by collagen proportionate area (CPA), α smooth muscle actin (αSMA) staining, quantitative analysis of hydroxyproline, and expression of genes mediating fibrogenesis (Acta2, Col1a1, Tgfb-1, and Timp1)." (PMID 34535664, 2021).
liver fibrosis (continued). "Other known liver fibrosis-related genes, ASMA, TGFB1, and TGFBR1, were not suppressed at the non-toxic concentration, suggesting that apigenin’s effect is directed to a specific subset of fibrogenesis-related pathways." (PMID 28256512, 2017).
renal fibrosis (2,079 papers, 2005 to 2026). A final common manifestation of a wide variety of chronic kidney diseases characterized by glomerulosclerosis and tubulointerstitial fibrosis. "TGF-β (the protein encoded by Tgfb1 gene) is also recognized as the primary mediator of renal fibrosis." (PMID 39047106, 2024). "Transforming growth factor–β (TGF-β; the protein encoded by Tgfb1 gene) is also the key mediator of renal fibrosis." (PMID 39047106, 2024). "Both INV-202 groups exhibited a significant reduction in renal fibrosis compared with the vehicle group, which was associated with a decrease in Tgfb1 expression." (PMID 37675364, 2023). "While inhibition of TGFβ1 attenuates renal fibrosis and progressive loss of kidney function in animal models of CKD, adverse effects limit the clinical utility of its inhibition." (PMID 36717814, 2023). "Taken together, for the last part, we reviewed the recent studies on the cytokines like TGFβ1 and Angiotensin II and genes such as Dab2, Rab7, and Manba, affecting tubular endocytosis, eventually causing renal fibrosis." (PMID 37799275, 2023). "Recently, RICTOR has been implicated in renal fibrosis development, specifically in association with TGFB1-induced fibroblast activation and epithelial–mesenchymal transition." (PMID 34063776, 2021). "TGFβ1-linked renal fibrosis has been shown to associate with miR-192 and miR-200; however, TGFβ1 has shown inconsistent effects on miR-192 expression in various in vivo and in vitro models." (PMID 31474862, 2019). "TGF-β1 (Tgfb1) is a profibrotic growth factor and is closely associated with matrix accumulation and renal fibrosis." (PMID 28429785, 2017). "The cytokine transforming growth factor beta 1 (TGF-β1) has been widely implicated in the development and progression of renal fibrosis in chronic kidney disease (CKD) in humans and in experimental models." (PMID 27387717, 2016). "The effect of TGFβ1 gene polymorphism in LN patients is still very little studied, especial studies that are associated with renal fibrosis of LN." (PMID 25279306, 2014). "The influence of T869C gene polymorphism on TGFβ1 production and renal fibrosis was evaluated in this study." (PMID 25279306, 2014). "The transforming growth factor beta 1 (TGF-β1) pathway is associated with renal fibrosis." (PMID 39858257, 2025). "Next, we aimed to assess whether genes upregulated in response to TGFβ1 were also associated with renal fibrosis." (PMID 36435939, 2022). "In summary, this study first confirmed that low dose of BV could cause obvious EMT-related renal fibrosis in vivo and in vitro, which was associated with the activation of the TGFβ1/Smad3 and Notch1/NICD signaling pathway." (PMID 35873571, 2022). "Dysregulation of TGFβ1 signaling is implicated in renal fibrosis." (PMID 32364526, 2020). "Given renin content and At1aR and Tgfb1 mRNA expression were enhanced in male hypoxia-exposed offspring, this may be an underlying molecular mechanism for the widespread renal fibrosis in this group." (PMID 28811528, 2017). "The functional TGFβ1 promoter SNP C-509 associates with renal fibrosis and asthma." (PMID 26656423, 2015). "Therefore, the effects of T869C gene polymorphism on TGFβ1 transport, TGFβ1 production and renal fibrosis still need to be elucidated." (PMID 25279306, 2014). "Hence, we further demonstrated that BV treatment could promote EMT and fibroblast-like properties’ acquisition in renal tubular epithelial cells through TGFβ1 and Notch1-mediated fibrotic signaling responses, all of which eventually caused renal fibrosis." (PMID 35873571, 2022). "Additionally, SIRT3 in the DKD model was associated with TGFβ1-mediated renal fibrosis." (PMID 35774140, 2022). "Moreover, ROS may promote the expression of profibrotic molecules, such as transforming growth factor-beta 1 (TGF-β1), therefore playing a major role in the development of renal fibrosis, a progressive and usually irreversible process, causing CKD." (PMID 34680522, 2021).
renal fibrosis (continued). "Furthermore, the TGFβ1/Smads signal transduction pathway was activated and caused renal fibrosis." (PMID 28208683, 2017). "Deposition of extracellular matrix (ECM) or fibrosis is an important type of healing response in the kidney, which can impair the function of the affected renal parenchyma, and TGFb1 is a pivotal mediator in the process of renal fibrosis." (PMID 40182573, 2025). "In this study, we found that Gal3 binds to TGFBR2, potentiating the effect of TGFβ1 and promoting renal fibrosis, consistent with reports of Gal3‐induced fibrosis in other organs." (PMID 40799164, 2025). "A 2017 study had also shown that DHA can inhibit TGFβ1-stimulated fibroblast activation; these cells play an essential role in the production of extracellular matrix and the progression of renal fibrosis." (PMID 40243751, 2025). "A study showed that EGCG improved renal fibrosis by inhibiting transforming growth factor‐beta 1 (TGF‐β)/mothers against decapentaplegic homolog 3 (Smad3) pathway in diabetic mice." (PMID 41019174, 2025). "Given the established role of the TGFβ1 signaling pathway in the pathogenesis of renal fibrosis, the expression levels of TGFβ1 and its downstream effector, Fibronectin, were determined in the kidneys of db/db mice by Western blot." (PMID 40926987, 2025). "TGFβ1 promotes renal fibrosis during CKD progression partly by inducing EMT of proximal tubular cells." (PMID 39887648, 2025). "The augmented TGFBR2 and TGFβ1 levels in diabetic kidneys potentiate the TGFβ1 signaling pathway, thereby facilitating renal fibrosis development." (PMID 40799164, 2025). "This binding inhibits the ubiquitin‐proteasome‐mediated degradation of TGFBR2 and increases TGFβ1 levels, thereby enhancing the profibrotic effects of the TGFβ1 signaling pathway and promoting the progression of renal fibrosis and DKD." (PMID 40799164, 2025). "It revealed a novel pattern by which Gal3 regulates TGFβ1 signaling in renal fibrosis, providing experimental insights for the development of therapeutic strategies for renal fibrosis and DKD." (PMID 40799164, 2025). "Smad3 is a key downstream factor of TGFβ1, and STAT3 acts downstream of many membrane receptors associated with renal fibrosis, including TGF βreceptors." (PMID 41275091, 2025). "ROS most likely employ their interaction with the TGF-β1 (transforming growth factor-beta 1) pathway to favor the progression of renal fibrosis as the individual ages." (PMID 40722862, 2025). "First, MSCs reduce the expression of transforming growth factor β1 (TGFβ1) and inhibit the transdifferentiation of glomerular cells into myofibroblasts, which is a key pathological process in renal fibrosis." (PMID 40959421, 2025). "DHA significantly reduced TGFβ1-induced fibroblast activation in a time- and dose-dependent manner, and these data suggest a positive action in modulating renal fibrosis." (PMID 40243751, 2025). "Their findings demonstrated that these gold NPs exhibited nephroprotective effects, including the attenuation of renal fibrosis, as evidenced by reduced levels of transforming growth factor-beta 1 (TGF-β1) and matrix metalloproteinase-2 (MMP-2)." (PMID 40427546, 2025). "LIPUS drastically downregulated the mRNA levels of renal fibrosis markers, such as Tgfb1, Serpine1, Fn1, and Acta2." (PMID 40729113, 2025). "Transforming Growth Factor Beta 1 (TGFb1) has shown a role in the pathogenesis of different urologic diseases, particularly renal fibrosis." (PMID 40182573, 2025). "6-Gingerol has been shown to inhibit renal fibrosis through various mechanisms, including the suppression of transforming growth factor-beta 1 signaling and the inhibition of fibroblast activation and extracellular matrix deposition." (PMID 39033184, 2024). "Treml4_Mono and Fn1_Mac expressed a variety of similar chemokines, such as Csf1r, Lrp1, Ccl6, and Tgfb1, and the latter protein promoted early repair but was involved in renal fibrosis during the progression of AKI-CKD." (PMID 38258908, 2024).
renal fibrosis (continued). "Mechanistically, GDF15 inhibits renal fibrosis by suppressing the transforming growth factor-beta 1 (TGF-β1)-mediated epithelial-mesenchymal transition (EMT) and fibroblast activation." (PMID 38892145, 2024). "Allicin decreased albuminuria and renal fibrosis, accompanied by reduced expression of TGFβ1 and p-ERK1/2 in a rat model of STZ-induced diabetic nephropathy." (PMID 38732588, 2024). "Since renal fibrosis is an important contributor to the progression of abnormal renal function, we examined the expression levels of TGFβ1 and α-SMA, which are both linked to renal fibrosis." (PMID 39195649, 2024). "A previous study showed that the PINK1 gene deletion markedly increased the transforming growth factor beta 1 (TGF‐β1) expression in renal tubular cells, and renal fibrosis." (PMID 37183600, 2023). "To assess circUBXN7 effects on fibrosis, we examined collagenI (Col-I) and transforming growth factor β1 (TGFβ1), which have been reported as renal fibrosis markers in renal tubular epithelial cells." (PMID 37744330, 2023). "Immunohistochemistry for α-SMA, TGFβ1, collagen I, and Masson’s staining showed that the renal fibrosis was most severe in the FXR−/−db/db mice." (PMID 37790634, 2023). "Our findings, in alignment with prior research, indicate the pivotal role of TGFβ1 in renal fibrosis onset." (PMID 37790634, 2023). "DNMT1 regulates MEG3 expression by altering the methylation level of the MEG3 promoter in TGFβ1-induced renal fibrosis, thereby affecting the development of renal fibrosis." (PMID 36869378, 2023). "To explore the possible mechanism of EA in attenuating renal fibrosis, we extracted total RNA from the control group, TGFβ1 group, and TGFβ1 + EA group cells and sequenced the transcriptome." (PMID 37831322, 2023). "The induction of glycolysis in renal fibrosis has previously been observed in vitro using cultured renal fibroblasts treated with TGFβ1, which aligns with our current findings." (PMID 37626891, 2023). "Taken together, combination therapy with DHA and BMSCs ameliorated podocyte injury and renal fibrosis in MN mice by downregulating the TGFβ1/Smad pathway." (PMID 36648018, 2023). "Quantitative PCR indicated a significant increase in the expression of renal fibrosis-related genes such as TGF-β1 (Transforming Growth Factor beta 1) and Col1a1 (collagen alpha-1 type 1) in the kidney of the CKD mice compared to control mice." (PMID 36460743, 2022). "In order to determine the function of EVs on renal fibrosis, we stimulated HK-2 cells with transforming growth factor-β1 (TGFβ-1) for 72 h, and then cultured them with BMSC-EVs." (PMID 35672285, 2022). "For example, in a UUO model on keratinocytes with overexpression of inactive TGFβ1, a decrease in the rate of renal fibrosis was shown, as well as in the case of Smad7 overexpression, which inhibits TGFβ1 signaling by a negative feedback mechanism." (PMID 35629404, 2022). "While TGFβ1 is an important cause of TEC pEMT and renal fibrosis, it has notable anti-inflammatory activities." (PMID 36470928, 2022). "TGFβ1 plays a regulatory role in the determination of renal cell fate and the progression of renal fibrosis." (PMID 36435939, 2022). "Fucoidan, isolated from Acaudina molpadioides, alleviated renal fibrosis and inflammation by decreasing the expression of transforming growth factor β1 (TGFβ1), plasminogen activator inhibitor 1, and phosphorylated Smad3 in diabetic mice." (PMID 36355016, 2022). "In conclusion, miR-154-5p can affect proliferation in glomerular mesangial cells via E3 ubiquitin ligase, Smurf1, regulating TGFβ1/Smads pathway, thus affecting renal fibrosis of DKD." (PMID 35126820, 2022). "TGFB1 promotes renal fibrosis by activating the Smad signaling pathway to transcriptionally regulate renal inflammation and fibrosis." (PMID 35327386, 2022).